EPO (erythropoietin)
Diseases named in the same sentence as EPO in open-access papers (continued):
Sharing a sentence is not in itself a finding about the gene and the disease.
anemia (continued). "ITPase deficiency would help in ribavirin dose reduction to a lesser extent and also support to use of less supportive agents such as blood transfusions and erythropoietin against anemia as treatment efficacy is reported to be hampered by dose reductions." (PMID 38468199, 2024). "EPO production in individuals with inflammation would fail at a later stage with Hb concentration decreasing, resulting in anemia." (PMID 39236809, 2024). "A submission will be made to the provincial Drugs and Therapeutics Committee to include erythropoietin in the drug schedule for district hospitals to treat anaemia." (PMID 39221724, 2024). "This enables the body to adjust progressively to hypoxic situations like anemia, and it aligns with the finding that elevated levels of EPO are found in patients with T-ALL." (PMID 38464517, 2024). "Anemia in patients with chronic kidney disease (CKD) often results from reduced erythropoietin (EPO) production, leading to lower levels of red blood cells and hemoglobin." (PMID 38962312, 2024). "Previous studies have shown that G-CSF and EPO have good synergistic effects on the treatment of anemia." (PMID 38953103, 2024). "This retrospective analysis highlights the efficacy of epoetin alfa in treating anaemia in patients with low-risk MDS, particularly those with low baseline EPO levels." (PMID 39463913, 2024). "Hyperthyroidism is also linked to anemia in CKD patients and can cause resistance to recombinant human erythropoietin." (PMID 39411618, 2024). "As testosterone stimulates erythropoietin and directly acts on the hematopoietic stem cells, anemia is a common feature of male hypogonadism." (PMID 37314685, 2024). "In cases of chronic kidney disease and in some malignancies, the production of endogenous erythropoietin is suppressed to a level that is insufficient to provide the necessary volume of red blood cells to prevent anemia." (PMID 39737166, 2024). "Recombinant human EPO used to treat anemia in chronic kidney disease due to low EPO production helped improve the cardiac function." (PMID 38628440, 2024). "Anemia can be a result of poor red blood cell production due to poor erythropoietin (EPO) production." (PMID 39189216, 2024). "Because the kidney is the main source of erythropoietin (EPO), CKD often leads to inadequate production of EPO in response to a given degree of hypoxia or anemia, which decreases oxygen delivery in the blood." (PMID 39256317, 2024). "Its use as a treatment for certain forms of anemia gained traction in the 1970s and remained in use until the dawn of recombinant erythropoietin (EPO) in the late 1980s." (PMID 39212549, 2024). "Many EPO-producing cells transform into myofibroblasts, resulting in inadequate the EPO production and exacerbation of anemia." (PMID 39845803, 2024). "EPO, due to its widespread application to treat anemia, is undoubtedly the recombinant product that has had the greatest clinical impact and generated by far the largest profit worldwide." (PMID 38672425, 2024). "Case 1: His initial anaemia improved with EPO and two red cell transfusions, and he continued on ruxolitinib enjoying an excellent quality of life for 2 years returning to cycling holidays and caring for his grandchildren." (PMID 39604140, 2024). "The production of erythropoietin, a major cytokine that affects the development of red blood cells, is triggered by a mechanism that detects low oxygen levels in anemia conditions." (PMID 38610814, 2024). "Often, the anemia occurs suddenly due to the development of EPO-neutralizing antibodies (Abs) eliminating the efficacy of both exogenous and endogenous EPO." (PMID 38528249, 2024). "Recombinant EPO is clinically used to treat secondary anemia in patients with chronic kidney disease and cancer." (PMID 38509204, 2024). "Currently, EPO and its analogs ESAs are mainly used for the treatment of anemia in chronic renal failure and malignancy." (PMID 38967734, 2024).
anemia (continued). "This compensative positive feedback on EPO production suggests a mechanism of anemia development downstream of EPO supply." (PMID 38512983, 2024). "Some of the more common paraneoplastic syndromes in RCC include hypercalcemia, anaemia, fever, cachexia, ectopic production of parathyroid hormone-related protein or erythropoietin and amyloidosis." (PMID 39651031, 2024). "Recombinant human erythropoietin (EPO) was given (10,000 U once a week for two weeks) to improve anemia symptoms." (PMID 38992582, 2024). "Erythropoiesis-stimulating agents (ESAs), including EPO, have been deployed in managing anaemia among CHF patients, albeit recent investigations have yielded conflicting outcomes concerning their efficacy." (PMID 39184703, 2024). "Despite the use of appropriate iron therapy and erythropoietin-stimulating agents, red blood cell transfusion is occasionally required, usually in the setting of acute bleeding or for correction of perioperative anemia." (PMID 39336553, 2024). "Collectively, these studies not only highlighted the critical need for effective anemia management strategies in dialysis patients but also paved the way for the development of erythropoietin as a targeted effective treatment modality." (PMID 39253627, 2024). "Although the status of the orphan drug extended the FDA approval to the use of EPO to treat anemia induced by AZT in patients with AIDS, the size of this patient population is also relatively small." (PMID 38672425, 2024). "For physician related, inadequacy targeting the anemia correction with folic acid and EPO was the highest recorded class of medication." (PMID 38771822, 2024). "Numerous studies, including a considerable number of randomized controlled trials, have consistently demonstrated the effectiveness of both EPO and DPO in treating anemia associated with CKD." (PMID 38313992, 2024). "Iron overload was described in patients with CKD before the introduction of erythropoietin due to frequent blood transfusions to correct anemia." (PMID 39121099, 2024). "Further understanding of the molecular mechanisms governing BFU-E self-renewal remains critical for developing effective treatments for EPO-resistant anemias." (PMID 39617757, 2024). "Literature also supports that if anemia is improved with Erythropoietin (EPO), CI will be decreased." (PMID 38827868, 2024). "This review article presents a comprehensive comparative analysis highlighting the advantages of DPO over EPO in the effective management of anemia, in both predialysis and dialysis-dependent (DD) CKD patients." (PMID 38313992, 2024). "Patients with sickle cell disease exhibit a decreased response to erythropoietin compared to non‐sickle patients, and the use of erythropoietin‐stimulating agents has shown effects toward alleviating anaemia." (PMID 39267208, 2024). "We found that by attenuating collagen fibrosis and inhibiting kidney enlargement, EEGS and selected metabolites increased EPO synthesis, thereby ameliorating anemia." (PMID 39845803, 2024). "This case report focuses on a 48-year-old female with chronic kidney disease (CKD) who received erythropoietin injections for CKD-related secondary anemia." (PMID 38989377, 2024). "Before the advent of erythropoietin as a therapeutic agent, testosterone was extensively utilized in the management of anemia in dialysis patients with end-stage renal disease (ESRD)." (PMID 39253627, 2024). "EPO, primarily recognized for its role in stimulating red blood cell production, holds promise in mitigating anaemia, reducing transfusion dependence, and possibly diminishing the frequency and severity of vaso-occlusive crises in SCA patients." (PMID 38463100, 2024). "In their study, patients with anemia were excluded and all the patients with a hemoglobin value of less than 13 g/dL received erythropoietin supplements pre-operatively." (PMID 38819771, 2024).
anemia (continued). "A comprehensive understanding of these factors is crucial for effective anemia management in CKD, emphasizing the need for a dual approach that addresses both EPO and iron deficiency." (PMID 38612557, 2024). "Currently, the first line of treatment for CKD anemia is erythropoietin-stimulating agents (ESAs) combined with iron therapy, which must be adequately metabolized to ensure the effectiveness of ESAs." (PMID 38672265, 2024). "Anemia in CKD is characterized by decreased EPO production and shortened red blood cell lifespan, necessitating iron supplementation to optimize hematologic parameters and mitigate symptoms." (PMID 38672265, 2024). "Anemia occurs in 34–94.3% CKD patients, mainly due to decreased renal erythropoietin, iron, folic acid, or vitamin B12 deficiency, poor erythrocyte survival, and blood loss during dialysis." (PMID 39831189, 2024). "Although several types of recombinant human erythropoietin are widely used to treat anaemia, the amount required to maintain target haemoglobin levels varies among patients." (PMID 39451618, 2024). "Previous studies showed that anemia in itai-itai disease was attributed to progressive renal damage, which resulted in the hypoproduction of erythropoietin, providing further support for the patient having “itai-itai disease”." (PMID 39111871, 2024). "Anemia was also noted in a recent study, associating it with rabbits infected with encephalitozoonosis, where the inflammation and the renal damage present in the disease could lead to an impaired erythropoietin production that explains this hematological change." (PMID 39770381, 2024). "Elevated RDW levels can reflect a state of inflammation, where erythropoietin-driven erythropoiesis maintains hemoglobin levels until anemia eventually occurs." (PMID 38971777, 2024). "In the presented case, post-nephrectomy, the patient experienced frequent hypotension and anemia during dialysis, improving with erythropoietin-stimulating agents and subsequently with rosuvastatin." (PMID 39221033, 2024). "Anaemia of chronic kidney disease (CKD) is a common complication in patients undergoing haemodialysis (HD), mainly due to the reduced renal production of erythropoietin, and is associated with a reduced quality of life and poor prognosis in this setting." (PMID 39451618, 2024). "Drug-induced kidney dysfunction can also contribute to hypoproliferative anemia through inadequate EPO production." (PMID 38628673, 2024). "Several mechanisms contribute to anemia of CKD, the main pathway being a relative erythropoietin (EPO) deficiency due to an insufficient production in the damaged kidneys." (PMID 39664943, 2024). "In India, cases of PRCA linked to recombinant human erythropoietin (rHuEpo) are underreported, likely due to limited awareness and diagnostic accessibility, despite prolonged use for CKD-associated anemia." (PMID 38989377, 2024). "It is also possible that non-dialysis patients performed poorly on the testing due to complications of CKD, such as uremia and anemia, which are often better controlled after dialysis initiation and concomitant initiation of erythropoietin therapy." (PMID 39070634, 2024). "Erythropoiesis-stimulating Agents (ESA) can stimulate EPO production, elevate hemoglobin levels, and ameliorate anemia, representing a primary therapeutic approach for addressing low hemoglobin levels in CKD patients." (PMID 39390059, 2024). "Patients with HF are more likely to have mixed anemia, of which the two most significant pathophysiological processes are iron shortage and inadequate erythropoietin production, according to a substantial body of clinical and fundamental research data." (PMID 39391392, 2024). "Anemia is a significant risk factor for adverse cardiovascular events in CKD patients, and EPO therapy has been associated with improvements in left ventricular function, exercise tolerance, and overall cardiovascular outcomes." (PMID 39200211, 2024).
anemia (continued). "Erythropoietin levels are generally elevated in individuals with malaria-induced anemia and cerebral malaria." (PMID 39492784, 2024). "While the kidneys have the function of secreting erythropoietin (EPO), many CKD patients exhibit reduced EPO secretion, leading to a situation where anemia and iron deficiency coexist." (PMID 39021564, 2024). "As a pivotal hormone regulating red blood cell production, EPO has revolutionized the treatment of anemia in patients with ESRD, leading to improved hemoglobin levels and alleviation of symptoms such as fatigue and weakness." (PMID 39835325, 2024). "Clinical studies have demonstrated that EPO can significantly improve the management of anemia in patients with chronic renal insufficiency." (PMID 39474425, 2024). "The multifactorial pathogenesis of postburn anemia includes direct erythrocyte destruction, suppressed marrow response to erythropoietin, and frequent phlebotomy." (PMID 39202529, 2024). "As past case report had shown the efficacy of Roxadustat in treating EPO-hyporesponsive anemia, we changed his rHuEPO to Roxadustat and his infection was brought under control quickly." (PMID 38528249, 2024). "In diabetes, chronic hyperglycemia and insulin resistance can impair erythropoietin production, contributing to anemia." (PMID 38172731, 2024). "Conversely, upon anemia or hypoxia, kidney‐derived erythropoietin (EPO) increases in response to upregulated hypoxia‐inducible factor (HIF) 2α." (PMID 38243847, 2024). "Roxadustat, the first HIF-PHI introduced globally, enhances EPO production within normal ranges, improves iron metabolism, and effectively treats anemia in chronic kidney disease." (PMID 38962312, 2024). "Erythropoietin is a kidney-produced hormone that stimulates erythrocyte production (erythropoiesis) in response to anemia or hypoxia." (PMID 39492784, 2024). "The second most frequently studied type was CKD anemia, and recombinant human erythropoietin was chosen as the basic treatment in all the included studies." (PMID 39338353, 2024). "Traditionally, erythropoiesis-stimulating agents (ESAs) such as recombinant human erythropoietin (rEPO) alfa (epoetin alfa; Eprex®) have been employed to treat anaemia in various conditions such as chronic kidney disease (CKD) and chemotherapy-induced anaemia." (PMID 39463913, 2024). "This complex interplay can result in insufficient stimulation of EPO production, even in the presence of hypoxia or anemia." (PMID 38612557, 2024). "For over 3 decades, recombinant human EPO has been used to treat anemia in chronic kidney disease resulting in decreased transfusion requirement." (PMID 39284834, 2024). "Since HIF-1α stimulates erythropoietin (EPO) production in the kidney and thus enhances marrow production and maturation of reticulocytes, PHDi have been used successfully to treat anemia in chronic renal failure." (PMID 38365865, 2024). "It has been previously reported that chronic injury to renal tubules and interstitium leads to inadequate EPO synthesis and hence, anemia." (PMID 39670089, 2024). "Roxadustat, an oral HIF-PHI, improves iron bioavailability, stimulates endogenous EPO, and corrects anemia of renal disease." (PMID 38528249, 2024). "This retrospective study aimed to assess the efficacy of epoetin alfa in treating symptomatic anaemia in low-risk MDS patients, focusing on transfusion independence and its relationship with baseline erythropoietin (EPO) levels and haemoglobin (Hb) response." (PMID 39463913, 2024). "This included treatment with erythropoietin to improve anaemia in children with cancer (low quality evidence)." (PMID 38481215, 2024). "Early interventions for patients with anemia, such as nutritional support, erythropoietin therapy, or blood transfusion when necessary, should be considered." (PMID 39839880, 2024). "We did not ask them specifically about the use of specific treatments (B12/folate/erythropoietin) for anemia." (PMID 40007691, 2024).
anemia (continued). "The expression level of EPO has important reference significance for hypoxia adaptability, anemia treatment, and muscle growth." (PMID 39199933, 2024). "Erythropoietin (EPO) is used in safe doses to control erythropoiesis, increase oxygen transport capacity by red blood cells, and treat anemia resulting from chemotherapy or chronic kidney disease." (PMID 39584970, 2024). "This peculiar mechanism of action was expected to correct anemia more effectively by increasing endogenous EPO production and simultaneously enhancing enteric iron absorption and iron mobilization (unlike ESAs)." (PMID 38705934, 2024). "A clinical sign of hypogonadism can be mild anemia as testosterone has the ability to increase erythropoiesis by stimulating erythropoietin production and expanding the number of erythropoietin-responsive cells in the bone marrow." (PMID 37674061, 2024). "The use of erythropoietin (EPO) therapy to treat anemia in CKD has been suggested to suppress the HPG axis as well." (PMID 39253627, 2024). "This feedback mechanism makes the anemia in CKD patients difficult to treat using erythropoietin analogues or iron supplementation." (PMID 39502472, 2024). "Although EPO has been used for more than three decades to treat anemia in patients with chronic kidney disease, the cardioprotective effects of EPO suggested in animal models have been difficult to demonstrate in humans." (PMID 38628440, 2024). "Treating dialysis-dependent patients with anemia, including daprodustat and other inhibitors of prolyl hydroxylase of hypoxia-inducible factor, recombinant human erythropoietin (rhEPO), and iron supplements." (PMID 38828426, 2024). "CKD affects anemia as the kidney produces erythropoietin (EPO), which is a signaling molecule that stimulates erythropoiesis." (PMID 38429779, 2024). "The treatment approach for nutritional anemia primarily involves supplying deficient nutrients, while CKD patients often necessitate intervention through recombinant human erythropoietin (rhuEPO)." (PMID 37960326, 2023). "Strategies include using EPO or its derivates to treat anemia and blocking the RAAS blockade to keep BF in peritubular capillaries." (PMID 38022248, 2023). "One-third of anemia in the elderly is classified as unexplained and studies have found that such anemia is characterized by low EPO levels, low inflammatory factors, and low lymphocyte counts." (PMID 36797683, 2023). "Overall, it seems that EPO can’t compensate completely for the anemia and low HB level in COPD patients." (PMID 37117600, 2023). "HIF-2α deficiency likely explains why chronic kidney disease is accompanied by anemia and blunted production of erythropoietin, as well as why impaired erythropoietin synthesis is accompanied by increased inflammatory and angiogenic markers." (PMID 37374094, 2023). "This resulted in moderate anemia with increased plasma erythropoietin and soluble transferrin receptor levels." (PMID 37234375, 2023). "At the cellular level, the production of EPO in REPs is regulated by a number of EPO-producing cells via an “on” or “off” mechanism, which changes explicitly in response to hypoxia and or anaemia." (PMID 37623232, 2023). "Concurrently, CKD and HF can contribute to anaemia development and progression via haemodilution, bone marrow suppression and reduced endogenous erythropoietin production." (PMID 35648270, 2023). "Anemia of patients with advanced CKD was treated with recombinant erythropoietin or erythropoiesis-stimulating agents (ESAs)." (PMID 37332579, 2023). "Current treatments for anaemia in CKD include parenteral injections of recombinant human EPO (rhEPO) or its analogues, and iron therapies, which attempt to increase erythrocyte production and development to correct the anaemia." (PMID 36048866, 2023). "Because this anemia is accompanied by a decrease in erythropoietin production, erythropoiesis‐stimulating agents (ESAs) can be expected to improve Hb levels." (PMID 37649390, 2023).